BDNF (brain derived neurotrophic factor)
Diseases named in the same sentence as BDNF in open-access papers (continued):
Sharing a sentence is not in itself a finding about the gene and the disease.
memory impairment (continued). "This study investigated the potential of Dex to mitigate MTX-induced neurotoxicity and memory impairment in rats and the possible role of the miR-15a/ROCK-1/ERK1/2/CREB/BDNF pathway." (PMID 36614208, 2023). "Ni, Al and Ni/Al mixture exhibited memory impairment by activation of oxidative stress, COX-2, and diminution of AChE, BDNF and NGF levels in cerebral cortex and hippocampus." (PMID 37841055, 2023). "A previous study showed that M. oleifera seed extracts improved the BDNF level together with CREB signaling activation in Sco-induced learning and memory impairment mice." (PMID 35299766, 2022). "plantarum C29 isolated from kimchi improved scopolamine-induced memory impairment in Morris water maze and Y-maze tests by inducing hippocampal p-CREB and BDNF expressions." (PMID 35624749, 2022). "GE effectively ameliorated aging-related memory impairment through increasing GSH, BDNF, Ach levels, and SOD activity." (PMID 35235140, 2022). "As predicted by network pharmacology methods, CASP3, BDNF, MAPK3, CREB1, and DRD2 were the hub genes in krill oil to alleviate METH-induced memory impairment." (PMID 34776973, 2021). "Furthermore, HemoHIM may attenuate memory impairment by activating the BDNF-ERK-CREB pathway." (PMID 33815562, 2021). "In HFD-fed mice, quercetin ameliorated the cognitive and memory impairment and enhanced the expression of phosphatidylinositol-4,5-bisphosphate 3-kinase (PI3K), PKB/Akt, Creb, and brain-derived neurotrophic factor (Bdnf)." (PMID 32785059, 2020). "The beneficial effects of ICS II on cerebral I/R-induced learning and memory impairment in vivo, and the detailed mechanisms of reciprocity between CREB/BDNF/TrkB and cGMP/PKG will be further elucidated in our next story." (PMID 32390851, 2020). "CREB activation can restore memory impairment in AD as the CREB-induced genes, such as brain-derived neurotrophic factor (BDNF) and insulin-like growth factor 1, can enhance neuron morphological outgrowth and formation of long-term and short-term memories." (PMID 32265696, 2020). "Therefore, memory impairments elicited by JWH-018 may also be due to decreases in BDNF." (PMID 31270353, 2019). "The change in the levels of BDNF and CREB proteins in the brain supplies a novel treatment strategy for the amelioration of memory impairment." (PMID 29973144, 2018). "Gagam-Palmultang has beneficial effects against scopolamine-induced memory impairments, which are exerted via modulation of the cholinergic system as well as the PI3K and ERK/CREB/BDNF signaling pathway." (PMID 29670659, 2018). "However, with the addition of NMDA and 7,8-DHF (NMDA receptor agonist and TrkB agonist), the inhibition of learning and memory of rats were improved, suggesting that the NMDA receptor and BDNF-TrkB signaling pathway may play a significant role in propofol-induced learning and memory impairment." (PMID 29621970, 2018). "In summary, scopolamine produced severe deficits in the performance of mice in the Morris water maze test, along with signs of memory impairments, including changed AChE activity and altered PI3K and ERK/CREB/BDNF pathways in the hippocampus." (PMID 29670659, 2018). "In another study, berberine significantly decreased the expression of the proinflammatory cytokines Cox-2, IL-1β, and TNF-α and markedly restored levels of BDNF and CREB and reduced the escape latency in rats with scopolamine-induced memory impairments." (PMID 26075266, 2015). "However, the role of hippocampal BDNF in arsenic-induced memory impairment remains unknown." (PMID 26368803, 2015). "The ETS-induced decrease in BDNF levels in infancy is consistent with the reductions in the synapsin, synaptophysin and PSD95 protein levels, as well as the learning and memory impairments observed at this age." (PMID 26305213, 2015).
memory impairment (continued). "Ampakines are thought to enhance memory because of interactions with BDNF (Brain Derived Neurotrophic Factor), which has been shown to correct hippocampal LTP in some disorders impacted by memory impairment." (PMID 22043169, 2011). "Their study suggested that atorvastatin might mitigate hypercholesterolemia-induced memory impairment by modulating PSD-95 and BDNF gene expression pathways, potentially offering protective effects." (PMID 40129866, 2025). "We found that SCEP significantly improved the cognitive and memory impairment of the AD mouse model and reduced AD pathology by suppressing HDAC3, in turn increasing the expression of BDNF and NT3 via gut microbiota and SCFAs, suggesting that SCEP can slow down the progression of AD." (PMID 40732937, 2025). "It significantly modulated the oxidative stress markers (SOD, GSH, CAT, MDA, and NO), inflammatory cytokines (IL-6, IL-1β, TNF-α), neurotrophic factors (CREB, BDNF), apoptotic markers (NFkB, caspase-3, caspase-9), and neurotransmitters (NE, DA, and GABA) in METH-induced memory-impaired rats." (PMID 41010958, 2025). "In addition, it was reported that L. rhamnosus GG intake improved cognitive and memory impairment by increasing the expression of SYP, PSD-95, and BDNF in an ethanol-exposed mouse model." (PMID 40002326, 2025). "Our previous study demonstrated that acute sleep deprivation increases the enzymatic cleavage of TrkB‐FL, a receptor for brain‐derived neurotrophic factor (BDNF), through activation of the basal forebrain PIEZO1/Ca2+/calpain pathway, leading to curtailed BDNF signaling and memory impairments." (PMID 37485782, 2024). "Elevations of BDNF in the brain circuits involved in IA memory consolidation and reconsolidation following BRB supplementation can supply a potential role in T. gondii-induced memory impairment therapies." (PMID 37649038, 2023). "Also, sodium butyrate treatment re-established brain-derived neurotrophic factor (BDNF) and glial cell line-derived neurotrophic factor (GDNF) expression, preventing memory impairment in experimental pneumococcal meningitis." (PMID 35606817, 2022). "Brain-derived neurotrophic factor (BDNF) and cAMP response element-binding protein (CREB) signaling have also interacted with acrylamide and alteration of these mechanisms ultimately induce learning or memory impairment and disturbed motor coordination." (PMID 36249258, 2022). "This indicates that GH improves the scopolamine-induced decrease in the expression level of BDNF as well as ERK/CREB phosphorylation in the mouse brain, which may be involved in alleviating memory impairment." (PMID 35126824, 2022). "Dysregulation of BDNF levels or signalling, decrease of synaptogenesis and alterations in neuronal network formation and function represent common KEs described in different DNT-relevant AOPs, all leading to learning and memory impairment in children." (PMID 34455033, 2021). "BDNF is involved in the pathogenesis of PTSD and related memory impairments." (PMID 33152026, 2020). "For example, a transient increase in GCs exhibits neuroprotective effects by activating TrkB/Akt signaling, while chronic stress or prolonged exogenous GC administration suppresses hippocampal BDNF and CREB expression, leading to neuronal apoptosis and memory impairment." (PMID 33100225, 2020). "We demonstrated that EAEP protected against scopolamine-induced memory impairment, and that the neuroprotective effects of EAEP may regulate the cholinergic nervous system, the antioxidant defense system, and the BDNF/TrkB/Akt-signaling pathway." (PMID 32679768, 2020). "ZMEO has a protective effect against memory impairment in rats with AD at least partly via reducing hippocampal AchE activity and enhancement of BDNF levels without a change in antioxidant status." (PMID 31031896, 2019).
memory impairment (continued). "Our results indicate that memory impairment following JWH-018 administration may be explained by the elevation of endocannabinoids and the suppression of BDNF in the hippocampus." (PMID 31270353, 2019). "The subsequent studies demonstrated that the PDE4 inhibitor rolipram was able to ameliorate Aβ1-42-induced learning and memory impairment by regulating the HPA axis, leading to increases in cAMP-related proteins such as the ratio of pCREB/CREB and BDNF expression." (PMID 30087608, 2018). "Similar activity was observed for soyasaponins Ab and Bb, which prevented scopolamine-induced memory impairment in mice without the inhibition of acetylcholinesterase by increasing BDNF expression and CREB phosphorylation." (PMID 26483842, 2015). "The memory impairments induced by Aβ1–42 were corrected with an intra-hippocampal infusion of BDNF, whereas NGF and NT-3 did not produce these effects." (PMID 25849905, 2015). "Increased inflammatory responses, down-regulated BDNF and TrK B expressions, and up-regulated APP and p75 expressions may contribute to memory impairment after subacute or chronic IL-1 administration." (PMID 23651534, 2013). "For example, in one rodent model, the IH intervention after the ischemic event lead to increased expression of brain derived neurotrophic factor (BDNF), increased hippocampal neurogenesis and functional synaptogenesis, as well as in improvement in spatial learning and long-term memory impairment." (PMID 24349453, 2013). "However, T. gondii alternations in BDNF expression in corticolimbic structures, in particular, whether BRB can improve its induced memory impairment have been less understood." (PMID 37649038, 2023). "However proBDNF, the precursor protein of BDNF, with an opposite effect on neuronal plasticity through binding to the p75 receptor, was increased in the hippocampus, which mainly contributes to ageing-related memory impairments." (PMID 37504929, 2023). "Despite the absence of pronounced memory impairments in the late post-hypoxic period, it is important to note that animals with increased expression of both BDNF and GDNF lacked the strategy of chaotic search in the Morris maze, which indicates an improvement in cognitive and mnestic functions." (PMID 36077134, 2022). "When we performed a probe test at 24 h after the last training trial, the untreated APP/PS1 Tg mice showed no preference for the target quadrant, which indicated significant memory impairment, whereas the BDNF-treated APP/PS1 Tg mice performed better than the non-treated APP/PS1 Tg mice." (PMID 28377712, 2017). "This also indicated that the expression of ChAT, BDNF and CREB-immunopositive neuronal cells in the hippocampus of rats treating acupuncture stimulation of GV20, but not of TE4 or the tail, restored memory impairment-related cholinergic function, and activated BDNF and CREB expression." (PMID 25231482, 2014). "Furthermore, they may prevent memory impairment by regulating the expression of neurotrophic factors such as glial cell line-derived neurotrophic factor (GDNF) and brain-derived neurotrophic factor (BDNF)." (PMID 38612870, 2024). "Similarly, BDNF overexpression in 5× familial AD (5-FAD) mice promoted the recovery of SYN and postsynaptic density protein-95 (PSD-95) as well as the number of presynaptic vesicles at excitatory synapses, enhanced long-term potentiation (LTP), and thus improved memory impairment." (PMID 36211826, 2022). "Thus, we could not dissociate the potential effects of lower BDNF and lower physical exercise on memory impairments in the present study." (PMID 33020545, 2020). "However, whether basal forebrain BDNF/TrkB pathway is involved in memory impairment followed by acute sleep deprivation is not clear." (PMID 32157827, 2020).
memory impairment (continued). "This also indicated that the expression of CHT1, VAChT, BDNF and CREB mRNAs in the hippocampus in rats treating acupuncture stimulation of GV20, but not of TE4 or the tail, restored memory impairment-related cholinergic function, and activated BDNF and CREB mRNAs expression." (PMID 25231482, 2014).
mood disorder (283 papers, 2010 to 2026). A cognitive disorder a disturbance in which the person's mood is hypothesized to be the main underlying feature. "Epigallocatechin-3-gallate (EGCG) and curcumin are polyphenols with evidence to support their positive impacts on mood disorder symptomology and potential mood-associated biomarkers like brain-derived neurotrophic factor (BDNF)." (PMID 41830024, 2026). "BDNF is essential for neuronal survival and plasticity, and its dysregulation can lead to cognitive deficits and mood disorders commonly associated with chronic stress." (PMID 40004109, 2025). "Downregulation of BDNF has been linked to neuronal atrophy, particularly in the hippocampus, and the subsequent development of stress-related mood disorders." (PMID 39896238, 2025). "With a much narrower focus, the Val66Met polymorphism reflecting a marked reduction in BDNF secretion in Met carriers renders those carriers more susceptible to stress-induced mood disorders." (PMID 40362507, 2025). "For example, polymorphisms in genes encoding neurotrophic factors such as BDNF increase susceptibility to mood disorders and alterations in neuroplasticity." (PMID 40244068, 2025). "In response to chronic stress, proinflammatory cytokines (such as TNF-α, IL-6, and IL-1β) and glucocorticoids exert a repressive effect on the BDNF gene, contributing to brain atrophy and the development of mood disorders in susceptible individuals." (PMID 39595869, 2024). "First, they underscore the potential of BDNF as a diagnostic biomarker for mood disorders and a target for therapeutic interventions." (PMID 39493096, 2024). "The strong inverse connection between BDNF levels and the severity of mood disorders highlights the potential of BDNF as both a diagnostic indicator and a target for therapeutic interventions." (PMID 39493096, 2024). "This study investigated the impact of the Val66Met mutation on BDNF, crucial in mood disorders' pathophysiology." (PMID 38252222, 2024). "Lower methylation levels of BDNF have been associated with increased symptom severity and susceptibility to stress-induced mood disorders." (PMID 38792892, 2024). "The Val66Met polymorphism of the BDNF gene has been implicated in increasing genetic vulnerability to mood disorders in response to environmental stimuli." (PMID 39203753, 2024). "Age-related cognitive declines and mood disorders are linked to disturbances in the hippocampal levels of 5-hydroxytryptamine (5-HT) and brain-derived neurotrophic factor (BDNF), which exert modulatory function in the synaptic plasticity and neurogenesis." (PMID 39149553, 2024). "Neuroimaging studies further corroborate this, showing structural brain abnormalities associated with low BDNF levels in mood disorders." (PMID 39493096, 2024). "It was shown that VNS influences neurotransmitters implicated in mood disorders, such as serotonin and norepinephrine, and increases the brain-derived neurotrophic factor (BDNF), also increased by pharmacological antidepressants." (PMID 38473935, 2024). "Lower BDNF levels are associated with mood disorders and symptom severity, indicating their potential as a biomarker." (PMID 39493096, 2024). "BDNF signaling in the CNS has long been implicated in the pathophysiology of mood disorders in humans." (PMID 37973914, 2023). "The PI3K-Akt pathway is a DRD2-linked signaling pathways that has been linked to thepathogenesis of mood disorders and BDNF-mediated neuroprotection." (PMID 36566472, 2023). "Improvement in mood disorders was associated with changes in pro-BDNF levels and the pro-BDNF/BDNF ratio in peripheral blood." (PMID 37958943, 2023). "It should be added, that chronic stress leads to a dysregulation of the hypothalamic-pituitary-adrenal axis, producing decreased BDNF levels, which has been described both in animal studies and in several studies related to stress-associated mood disorders." (PMID 36812175, 2023).
mood disorder (continued). "An abnormal profile of haemopoietic and neuronal growth factors, including BDNF, is observed in patients with mood disorders as well as in those at risk of developing AHT." (PMID 35455388, 2022). "Decreased expression of BDNF and upregulated proBDNF (precursor to BDNF) in brain have been implicated in the stress-induced mood disorders." (PMID 35462923, 2022). "BDNF is involved in the pathogenesis of mood disorders, and it has been associated with the action of antidepressant and anxiolytic drugs." (PMID 35589704, 2022). "Several studies have highlighted an increase of BDNF serum levels associated with stress and mood disorders." (PMID 36034425, 2022). "Stress, one of the major risk factors underlying mood disorders, decreases BDNF and its downstream signaling whereas antidepressant therapies exert their therapeutic effect, at least in part, through promotion of this signaling pathway." (PMID 35321093, 2022). "As prenatal exposure to maternal mood disorders significantly increases the risk of neurological conditions in later life, we also examined the possibility of placental BDNF transfer by developing a new mouse model." (PMID 33462179, 2021). "BDNF has also been implicated in the regulation of the stress response as well as the biology of mood disorders." (PMID 30867560, 2020). "For these reasons, peripheral BDNF was proposed as a potential diagnostic, prognostic, and therapeutic biomarker for mood disorders, particularly associated with disease severity and response to AD treatments." (PMID 32517269, 2020). "The improvement in mood disorders was associated with a change in peripheral pro-BDNF and in the pro-BDNF/BDNF ratio, suggesting that further investigation must address the role of the two neurotrophin isoforms investigated here." (PMID 31118969, 2019). "A large number of human and animal studies have implicated the close links between BDNF and the occurrence and treatment of various diseases, including schizophrenia, Alzheimer's disease, mood disorders, and Parkinson's disease." (PMID 31231295, 2019). "Mood disorders have been linked to the activity and productive state of neurotrophic substances specifically BDNF, thus increasing BDNF levels can be an efficient intervention." (PMID 29896129, 2018). "Brain-Derived Neurotrophic Factor (BDNF) Val66Met polymorphism has been associated with increased susceptibility to develop mood disorders and recently it has been also linked with cardiovascular disease (CVD)." (PMID 30347685, 2018). "In humans, stress at work reduced serum BDNF levels in hospital employees and traumatic events have been found to be associated with lower BDNF plasma levels in patients with mood disorders." (PMID 29348904, 2017). "In fact, we reported an association between BDNF concentrations and comorbid mood disorders in patients with cocaine use disorders." (PMID 29108028, 2017). "BDNF likely acts as a modifier gene or jointly with other genes in the same pathway to contribute to the risk of mood disorders." (PMID 26091093, 2015). "In humans, abnormally low levels of BDNF are associated with a smaller hippocampal volume and mood disorders including obsessive-compulsive disorder, and depression." (PMID 26257661, 2015). "Several GWA meta-analyses with thousands of individuals have been conducted for MDD and BPD, however, none of these studies reported suggestive signals for the association of the Val66Met marker or other genetic variants of BDNF with mood disorders." (PMID 26091093, 2015). "Stress is considered an important environmental stimulus that influences the risk of mood disorders by altering the expression of BDNF." (PMID 26091093, 2015). "Some studies have examined the relationship between BDNF protein level and neuropsychiatric disorders in the hope of identifying useful peripheral biomarkers for predicting the risk of mood disorders." (PMID 26091093, 2015).